RN7SL1 (RNA component of signal recognition particle 7SL1)
Synonyms: 7SL; 7L1a; RNSRP1; RN7SL
Gene: Miscellaneous RNA gene on chromosome 14 (49,586,580 to 49,586,878, forward strand). Ensembl gene ENSG00000276168.
Gene Ontology:
Biological process: SRP-dependent cotranslational protein targeting to membrane, signal sequence recognition
Cellular component: signal recognition particle, endoplasmic reticulum targeting
Homologues: Orthologues: macaque Metazoa_SRP (99% identical), chimpanzee Metazoa_SRP (99% identical), dog Metazoa_SRP (99% identical), mouse Rn7s1 (99% identical), rabbit Metazoa_SRP (99% identical), rat Metazoa_SRP (99% identical), pig Metazoa_SRP (98% identical). Paralogues in human: RN7SL2 (99% identical), RN7SL3 (98% identical), RN7SL230P (89% identical), RN7SL5P (89% identical), RN7SL126P (89% identical), RN7SL296P (88% identical), RN7SL45P (88% identical), RN7SL769P (88% identical), RN7SL220P (88% identical), RN7SL664P (88% identical), RN7SL7P (88% identical), RN7SL357P (87% identical), and 708 more.
Diseases named in the same sentence as RN7SL1 in open-access papers:
RN7SL1 is named in the same sentence as 11 diseases in open-access papers, as found by Europe PMC text mining. Sharing a sentence is not in itself a finding about the gene and the disease. The quoted sentences say what the papers report.
breast carcinoma (12 papers, 2017 to 2023). "Another Pol III template targeted by ERα is the RN7SL1 gene, which is strongly implicated in breast cancer pathology by inducing inflammatory responses in tumours." (PMID 35143945, 2022). "The group reported that exosomes mediate the RN7SL1 transfer from stromal cells to breast cancer cells: 5‐ethynyl uridine‐modification by azide‐linked fluorescein allowed to see the horizontal acquisition of stromal cell RNA, represented by transcripts regulated by POL3 besides RN7SL1." (PMID 33391635, 2020). "After exosome transfer to breast cancer cells, unshielded RN7SL1 can activate breast cancer RIG-I and promote tumor growth, metastasis, and therapy resistance." (PMID 34607567, 2021). "Only RN7SL1 was inconsistently expressed in different types of breast cancer cells under shikonin treatment." (PMID 29422643, 2018). "Assessments of the blood samples of breast cancer patients revealed the presence of unshielded RN7SL1 in exosomes." (PMID 29558960, 2018). "Delivering unshielded RN7SL1 to breast cancer cells facilitates cancer growth, metastasis, and therapy resistance through retinoic acid-inducible gene I (RIG-I) signaling." (PMID 29282096, 2017). "As a result, RN7SL1 delivered by exosomes to breast cancer cells activates RIG-I signaling." (PMID 36798121, 2023). "•ER also targets RN7SL1 gene that promotes breast cancer progression." (PMID 35143945, 2022). "Interestingly, triggering of stromal NOTCH‐MYC by breast cancer cells results in the increase of RN7SL1 and unshielded RN7SL1 in stromal exosomes." (PMID 30585399, 2019). "After the transfer of exosomes to immune cells, breast cancer cells, bone marrow, and dendritic cells, unshielded RN7SL1 triggered inflammatory responses, enhanced tumor growth, metastasis, and therapeutic resistance, in addition to inducing expression of CD40, CD86, PDL1, and MHCII." (PMID 29558960, 2018). "Interestingly, a recent report uncovered that, although many noncoding RNAs are present in the cytoplasm of breast cancer cells, a single RNA, RN7SL1, was sufficient to activate RIG-I signaling." (PMID 29590171, 2018). "However, breast cancer cells can stimulate stromal fibroblasts to produce stromal exosomes, which contain unshielded endogenous RNA (RN7SL1), via triggering NOTCH-MYC pathways." (PMID 29282096, 2017). "For instance, in breast cancer, SRP9/14 functions as an RNA binding protein to bind RN7SL1, shielding the virus-like inflammatory response." (PMID 35590292, 2022). "While RN7SL1 is shielded by SRP9 and SRP14 to avoid detection by RIG-I under normal circumstances, naked RN7SL1 is transferred to stromal exosomes following contact between fibroblasts and ISG-R breast cancer cells." (PMID 36798121, 2023). "Exosomes that deliver RN7SL1 ncRNA generated by RNA Pol III were identified as the pivotal link between activated stromal cells and RIG-I dependent activation of ISG signaling in breast cancer cells." (PMID 36798121, 2023). "Upon metastasis to breast cancer cells, activation of PRR RIG-I by unscreened RN7SL1 could enhance tumor growth, metastasis, and treatment resistance." (PMID 35242126, 2022). "Expanding these findings to human patients, we demonstrated that the serum of triple-negative breast cancer patients is enriched for unshielded RN7SL1, whereas serum from healthy individuals and patients with other breast cancer subtypes is not." (PMID 30823926, 2019). "Mechanistically, we demonstrated that when stromal fibroblasts and basal-like breast cancer cells interact, fibroblast-derived exosomal RN7SL1 is not bound by its canonical RBPs and can act as a potent activator of RIG-I in recipient breast cancer cells." (PMID 30823926, 2019).
colorectal cancer (1 paper, 2025). A primary or metastatic malignant neoplasm that affects the colon or rectum. "The Rn7sk, Rpph1, Rn7sl1, Rn7sl2, Znf460, Snord17, Snora73b, H1-4, H4c12, and H3c7 genes were discovered to be highly upregulated in the tumor tissue collected from colorectal cancer patients." (PMID 40427657, 2025).
hepatocellular carcinoma (1 paper, 2021). A malignant tumor that arises from hepatocytes. "Hepatocellular carcinoma patients with higher RN7SL1 concentrations also show lower survival rates." (PMID 34607567, 2021). "RN7SL1 may enhance hepatocellular carcinoma cell proliferation and clonogenic growth." (PMID 34607567, 2021).
lymph node metastasis (1 paper, 2023). "In addition, RN7SL1 fusions were also linked to lymph node metastasis, and TG fusions were related to follicular-variant tumors (p = 0.053, 0.076, respectively)." (PMID 36941725, 2023).
tumor (21 papers, 2018 to 2025). "CAR-T cells that expressed RN7SL1 were found to have better tumor infiltration, longer half-lives, and stronger antitumor activity." (PMID 37190280, 2023). "We can also eliminate poor tumor infiltration by decoding the complexities of IFN/PRR signaling and then engineering CAR T cells to deploy RN7SL1 to recode these signals in the tumor microenvironment." (PMID 36707873, 2023). "CAR-T cells transmit RN7SL1, an RNA derived from the body’s own cells, to the tumor through extracellular vesicles (EVs), which stimulate the body’s own T cells to seek cancer cells that do not recognize CAR-T cells." (PMID 37190280, 2023). "RN7SL1 CAR T cells exhibit good tumor infiltration, myeloid cell and DC production activation, a tumor microenvironment with antigen provision, and endogenous T cells to reject solid tumors under the threat of CAR antigen loss." (PMID 36707873, 2023). "Stimulation of RLRs in immune cells by RN7SL1 enhances anticancer immunity and enables tumor suppression when immune checkpoints are blocked." (PMID 36755342, 2023). "The authors demonstrate that RN7LS1-containing CAR T cells deliver RN7SL1 in EV in vivo, that orchestrates endogenous immune activation to improve responses against the tumor." (PMID 35269412, 2022). "Supported by these features, RN7SL1 CAR T-cells could perform an effective killing function even in a poorly immunogenic tumor." (PMID 37149643, 2023). "The anti-tumor efficiency of chimeric antigen receptor (CAR) T cells can also be improved by inducing the expression of the RNA Component Of Signal Recognition Particle 7SL1 (RN7SL1), secreted via EVs from CAR-T cells." (PMID 37175226, 2023). "Several researchers put forward an alternative strategy that CAR-T cells engineered to produce extracellular vesicles containing RN7SL1 by delivering the pattern recognition receptor agonists could effectively stimulate anti-tumor immunity." (PMID 36168626, 2022). "In addition, exosomes carrying unshielded RN7SL1 promoted tumor progression and metastasis through dependent activation of the pattern recognition receptor (PRR) retinoic acid-inducible gene I (RIG-I)." (PMID 29580275, 2018). "scRNA-seq performed on tumor tissues of mice infused with RN7SL1 CAR T-cells showed that RN7SL1 could reduce suppressive myeloid cell subsets, increase inflammatory DCs expressing costimulatory genes, and activate amplification of effector-memory endogenous CD8+ T cells." (PMID 37149643, 2023). "Thus, EV from CAR T cells may transport immunostimulatory RN7SL1 or other immunorelevant molecules, such as immunogenic peptides than can stimulate specific memory T cells to kill tumors, to the tumor microenvironment." (PMID 35269412, 2022). "The exosomes from CAR-T cells with signal recognition particle 7SL1 (RN7SL1, a noncoding RNA that activates interferon-IFN-stimulated genes) can orchestrate endogenous immune activation to improve responses against the tumor." (PMID 37528472, 2023). "More recently, an interesting paper demonstrated an in vivo role of the RNA component of signal recognition particle 7SL1 (RN7SL1, a non-coding RNA that activates interferon-IFN-stimulated genes) contained in EV from CAR T cells in tumor rejection." (PMID 35269412, 2022). "When unshielded RN7SL1 in circulating exosomes was taken up by the immune cells, it incited an inflammatory response by activating the PRR RIG-I and promoted tumor growth, metastasis and therapy resistance." (PMID 34073722, 2021). "While RN7SL1 activates RLR signaling in CAR-T cells and improves CAR-T cell function, the RN7SL1-loaded EVs are preferentially transferred to immune rather than tumor cells in the tumor microenvironment." (PMID 36755342, 2023). "It was found that most of the expanded CAR-T cell population that expressed RN7SL1 RNA showed a memory T-cell phenotype and persisted longer in both the tumor and the bloodstream than RN7SL negative CAR-T cells, which were quickly exhausted." (PMID 36798121, 2023).
tumor (continued). "These exosomes also transfer RN7SL1 to myeloid cells, DCs and T cells but not to tumor cells, which improves the immunostimulatory role of DCs and myeloid cells and effectively activates the function of endogenous CD8+ T cells against the tumor." (PMID 37528472, 2023). "Those CAR-T EVs improve immune activation against tumor cells, transferring RN7SL1 to endogenous immune cells, but not to tumor cells." (PMID 36831396, 2023). "RN7SL1 recipient cells, which are T, myeloid, and dendritic cells, activate IFN-dependent inflammatory responses, improving the immunostimulatory effects of dendritic and myeloid cells that end up in activation of CD8 T cells against tumor cells." (PMID 36831396, 2023). "EV released by CAR T cells upon CAR engagement transfer RN7SL1 to endogenous immune cells (myeloid cells, DC and T cells), but not to the tumor cells, and EV release and RN7LS1 transfer is inhibited by a nSMase inhibitor." (PMID 35269412, 2022). "engineered CAR T-cells to secrete RN7SL1, a non-coding RNA that activates RIG-I, via extracellular vesicles that are preferentially taken up by immune rather than tumor cells." (PMID 41019052, 2025). "When combined with immune checkpoint blockade, RN7SL1-CAR T-cells eradicated antigen-heterogeneous melanomas in immunocompetent mice and prevented tumor outgrowth upon rechallenge with antigen-negative tumor cells, suggesting the generation of CAR antigen-independent memory." (PMID 41019052, 2025). "Notably, RN7SL1 increased the functional longevity of CAR-T cells and sustained tumor clearance, which was not seen in systemic RN7SL1 delivery, indicating that tumor response depended on CAR-target interactions." (PMID 40948803, 2025).
cancer (6 papers, 2018 to 2025). A tumor composed of atypical neoplastic, often pleomorphic cells that invade other tissues. "7SL is encoded by RN7SL1 (RNA component of the signal recognition particle 7SL1) and possesses a small ORF (smORF) that has been shown to be translated into peptides in cancer." (PMID 41303378, 2025). "RN7SL1 causes the activation of an anti-viral signaling in the cancer cell, then leading to tumor growth and therapy resistance, while exosomal HISLA causes the activation of HIF1A, which favors glycolysis and chemoresistance in the targeted cancer cells." (PMID 35076579, 2022). "RN7SL1 was transferred to the cancer cells through fibroblast‐derived EVs." (PMID 29280568, 2018). "Activation of RIG‐I in the cancer cells led to NOTCH/MYC pathway activation in fibroblasts which, in turn, enhanced stromal RN7SL1 availability, thus establishing a positive feed‐back loop." (PMID 29280568, 2018).
RN7SL1 also shares sentences with these, for which no sentence is quoted: Alzheimer disease (1 paper); COVID-19 (1); glioma (1); melanoma (1); virus infection (1).